TFPI (tissue factor pathway inhibitor)
Diseases named in the same sentence as TFPI in open-access papers (continued):
Sharing a sentence is not in itself a finding about the gene and the disease.
invasive ductal carcinoma (1 paper, 2018). "We observed significantly lower activity of TFPI and significantly higher concentration of PAI-1 in the group of patients with invasive ductal carcinoma as compared with invasive lobular carcinoma (P=0.0248, P=0.0275 respectively)." (PMID 29475895, 2018). "We observed significantly lower activity of TFPI and significantly higher concentration of PAI-1 in the group of patients with invasive ductal carcinoma as compared with invasive lobular carcinoma." (PMID 29475895, 2018).
ischemia (1 paper, 2013). A hypoperfusion of the BLOOD through an organ or tissue caused by a PATHOLOGIC CONSTRICTION or obstruction of its BLOOD VESSELS, or an absence of BLOOD CIRCULATION. "Additional new genetics may further improve thromboregulation (e.g., tissue factor pathway inhibitor [TFPI], endothelial protein C receptor [EPCR], CD39) or reduce inflammation (HO-1, TNFRI-Fc, A20, CD39) and ischemia–reperfusion injury (CD39, HO-1)." (PMID 25098626, 2013).
liver diseases (1 paper, 2022). "Plasma levels of tissue factor pathway inhibitor (TFPI) in patients with liver diseases tend to be normal, though significantly lower levels have also been reported." (PMID 35518552, 2022).
liver dysfunction (1 paper, 2024). "High levels of TFPI were associated with AKI, liver dysfunction, DIC and a high SOFA score." (PMID 38914630, 2024). "Furthermore, TFPI elevations were apparently associated with AKI and parameters of liver dysfunction." (PMID 38914630, 2024).
lupus nephritis (1 paper, 2019). Glomerulonephritis in the context of systemic lupus erythematosus. "This study evaluates the utility of urinary pro-thrombotic molecules such as tissue factor (TF), anti-thrombotic molecules such as tissue factor pathway inhibitor (TFPI), and fibrinolytic molecules such as plasmin and d-dimer as biomarkers of lupus nephritis (LN)." (PMID 31319876, 2019).
metabolic syndrome (1 paper, 2017). A cluster of metabolic risk factors for CARDIOVASCULAR DISEASES and TYPE 2 DIABETES MELLITUS. "On comparing hemostatic markers, TFPI and PC were the only hemostatic markers that were significantly raised in those with metabolic syndrome compared to those without (12.7 ± 4.1 vs. 15.2 ± 5.3,p = 0.012 and 111 ± 18 vs. 119 ± 20,p = 0.05, respectively)." (PMID 31249920, 2017).
metastatic cancer (1 paper, 2015). A carcinoma which has spread from the original site of growth to another anatomic site. "These authors also observed that TFPI activity was higher in metastatic cancer patients." (PMID 25882602, 2015).
metastatic colorectal cancer (1 paper, 2009). "Up-regulation of TFPI mRNA is associated with human metastatic colorectal cancer." (PMID 19200380, 2009).
morbid obesity (1 paper, 2017). An excess of body weight, normally defined as an individual with a body mass index greater than 35 or a body weight greater than one hundred percent of ideal body weight. "There were significant differences in the activity of coagulation factors and natural anticoagulant as shown inTable 2, with FVII, FVIII, PC, FPS, and TFPI significantly increased in morbid obesity and AT significantly reduced." (PMID 31249920, 2017).
myeloproliferative neoplasm (1 paper, 2019). A clonal hematopoietic stem cell disorder, characterized by proliferation in the bone marrow of one or more of the myeloid (i.e., granulocytic, erythroid, megakaryocytic, and mast cell) lineages. "The role of TFPI in the pathogenesis of thrombosis in myeloproliferative neoplasms is not entirely clear." (PMID 30781507, 2019).
ovarian hyperstimulation syndrome (1 paper, 2021). A complication of ovulation induction in infertility treatment. "Interestingly, TFPI-1 levels in blood, but not in follicular fluid, are significantly different between patients with ovarian hyperstimulation syndrome (OHSS) and non-OHSS patients." (PMID 33794911, 2021).
pneumococcal pneumonia (1 paper, 2015). A febrile disease caused by STREPTOCOCCUS PNEUMONIAE. "In the present study we did not observe lung hemorrhage in either study group and nebulization of rats with rh-TFPI did not importantly affect inflammation or lung pathology, which was in line with previous reports on pneumococcal pneumonia in rodents." (PMID 25992779, 2015).
polycythemia (1 paper, 2024). Abnormally high mass or concentration of red blood cells in the blood, either due to an increase in erythropoiesis or a decrease in plasma volume. "To investigate the relevance of blood coagulation to erythropoiesis, we initially assessed plasma TF and TFPI in healthy controls and polycythemia patients with JAK2V617F mutation." (PMID 38729948, 2024). "To explore whether TFPI inhibition had therapeutic efficacy against polycythemia, we treated Jak2V617F-mutated mice with TFPI mAb." (PMID 38729948, 2024). "To examine the role of TFPI in polycythemia development, we crossed Vav-iCre;Jak2V617F/+ mice with TFPIf/f mice and analyzed the resulting double mutant Jak2V617F;TFPIf/f;Vav mice." (PMID 38729948, 2024). "The results found that TFPI mAb treatment reduced erythropoiesis in polycythemia." (PMID 38729948, 2024). "Furthermore, TFPI blockade impairs human erythropoiesis in vitro, and normalizes the erythroid compartment in mice with polycythemia." (PMID 38729948, 2024). "TFPI mAb treatment similarly decreased PB RBC numbers and Hb, and reduced F4/80+CD169+Vcam-1+ macrophage heme content in hypoxia-induced polycythemia mice." (PMID 38729948, 2024).
pregnancy disorder (1 paper, 2021). A disorder that is related to pregnancy. "We found in our study that genetic changes, localized in SNPs from CSF2, FLT1, TFPI and TLR9 genes, were associated with PROM, when the results had been adjusted for APTT, PLT parameters or pregnancy disorders." (PMID 34828331, 2021). "An additional comparison between the pPROM and tPROM cases showed that the C alleles for the CSF2, FLT1 and TFPI polymorphisms, and the T allele for the TLR9 SNP in different complex variants, were more common in the women with pPROM after adjusting for APTT, PLT parameters and pregnancy disorders." (PMID 34828331, 2021).
progeria (1 paper, 2022). "Applying these stricter standards, three of the genes that are differentially expressed in aging and progeria (TFPI, STAT1, IGFBP2) appear to be associated with changes in protein expression." (PMID 36289702, 2022).
psoriasis (1 paper, 2020). An autoimmune condition characterized by red, well-delineated plaques with silvery scales that are usually on the extensor surfaces and scalp. "We found one crossover locus of IL13 for psoriasis, two crossover loci BLK and ITGAM/ITGAX genes for SLE and four crossover loci near TFPI, CYP2A1, PECAM1, and CXCL12 for CAD data set." (PMID 32779262, 2020).
rheumatoid arthritis (1 paper, 2011). A chronic, systemic autoimmune disorder characterized by inflammation in the synovial membranes and articular surfaces. "TFPI could also be used to relieve rheumatoid arthritis (RA) synovial inflammation." (PMID 21941675, 2011).
systemic inflammatory response syndrome (1 paper, 2015). SIRS is a serious condition related to systemic inflammation, organ dysfunction, and organ failure. "They found activation of TF-dependent coagulation pathway not adequately balanced by TFPI has important roles in sustaining DIC and systemic inflammatory response syndrome." (PMID 26025445, 2015).
thrombotic microangiopathy (1 paper, 2025). The syndromes of microangiopathic hemolytic anemia, thrombocytopenia, and variable signs of organ impairment, due to platelet aggregation in the microcirculation. "Vascular damage can lead to a decrease in endothelial TFPI, as observed in thrombotic microangiopathy (TMA) patients with reduced TFPI levels." (PMID 39822757, 2025).
tonsillitis (1 paper, 2024). Inflammation of the tonsillar tissue. "Furthermore, complement and coagulation cascades, including MBL2, TFPI, and PROCR have been identified as biomarkers related to phenotypes such as tonsillitis." (PMID 39410993, 2024).
tumor metastasis (1 paper, 2017). "Multivariate regression revealed that TFPI-1 acted as a predictor for DVT or tumor metastasis in NSCLC patients [OR: 4.15 or 3.28, P < 0.05, resp.]." (PMID 28246607, 2017). "Finally, only symptomatic or doubtful DVT or metastasis patients were included, and we cannot exclude that asymptomatic DVT or metastasis which was present in some patients and potentially decreased the predicting power of TFPI-1." (PMID 28246607, 2017).
urothelial bladder cancer (1 paper, 2022). "TPST1 up-regulation is related to high pathological staging and low survival rate in patients with urothelial bladder cancer and a decreased level of tissue factor pathway inhibitor (TFPI)." (PMID 35204186, 2022).
uterine fibroids (1 paper, 2017). "Further adding evidence for TPFI as a causal candidate gene for uterine fibroids, a study comparing gene expression between uterine fibroid tissue and normal myometrial tissue reported 3.9 times lower expression of the TFPI gene in fibroid tissues, on average." (PMID 28715450, 2017).
tumor (70 papers, 2005 to 2025). "While complex context-dependent effects exist, TF exhibits many tumor-promoting properties, whereas its natural inhibitors TFPI-1 and TFPI-2 have been associated with tumor suppressor activity." (PMID 36900315, 2023). "The Tinzaparin (a low-molecular-weight heparin) can trigger tissue factor pathway inhibitor (TFPI) secretion from cancer cells, and also the recombinant TFPI induce suppression of tumor-derived exosomes causing migration of tumor cells." (PMID 29868251, 2018). "This is because TFPI has previously been recognized as a tumor suppressor in experimental studies, and because higher TFPI expression in tumors was associated with increased survival in the present study." (PMID 25882602, 2015). "Next, we evaluated if TFPI or TF SNPs were associated with any clinicopathological characteristics and molecular tumor subtypes." (PMID 25882602, 2015). "Results showed that the differentially expressed genes were significantly associated with tumor grade and ER status when either isoform of TFPI was overexpressed." (PMID 23071754, 2012). "Although there are limited reported findings on syndecan-3 in BC, existing evidence has suggested that syndecan-3 is linked to hypoxia-associated and glycolytic gene signatures and interacts with the tissue factor pathway inhibitor (TFPI), affecting tumour-associated coagulation." (PMID 41463344, 2025). "Furthermore, multivariate hazard ratio analysis of all tumors, showed that tumor size and lymph node status were highly associated with overall survival (P <0.00001) and abolished the effect of low TFPI expression (P >0.05)." (PMID 25882602, 2015). "Additionally, they revealed that the gene signatures following overexpression of either TFPI isoform were associated with tumor grade and ER status, and that TFPIα expression correlated with tumor size." (PMID 25882602, 2015). "Indeed, it has been suggested that tumor-associated TFPI may play a role in the reduction of hematogenous metastasis." (PMID 33947134, 2021). "The two isoforms of TFPI share the Kunitz-1 and Kunitz-2 domains and it therefore seems plausible that TFPI induced the anti-tumor effects through association with an unknown receptor, involving the first two Kunitz domains, resulting in the tyrosine phosphorylation of an ~75 kDa protein." (PMID 21849050, 2011). "LMWH also promotes the release of tissue factor pathway inhibitor (TFPI), thereby impairing tumor neoangiogenesis." (PMID 40469990, 2025). "To explore the roles of MMP1 and TFPI in the tumor microenvironment, we analyzed their expression distributions at the single-cell level." (PMID 41425594, 2025). "Coagulation proteins, especially tissue factor pathway inhibitors (TFPI), are major inhibitors of the tissue factor (TF)-dependent coagulation pathway and play a role in tumor proliferation and metastasis." (PMID 40765823, 2025). "Inhibitors of CD147, a transmembrane glycoprotein, and TFPI, a natural inhibitor of the coagulation pathway, have shown potential implications for inhibiting tumor progression, metastasis, and chemoresistance." (PMID 38360687, 2024). "TFPI has been found to play a complex role in cancer, with both tumor-suppressive and tumor-promoting effects depending on the context." (PMID 37759229, 2023). "Therefore, based on our current results, we hypothesise that elevated post-treatment plasma activity of TFPI results in the compensatory release of TFPI associated with up-regulation of the expression of TF both by tumour cells and endothelial cells damaged by adjuvant therapy." (PMID 37240751, 2023). "The overexpression of TFPI or the treatment of cells with its recombinant form induced apoptotic cell death in cancer cells and thus a tumor-suppressing function was attributed to the protein." (PMID 36980251, 2023). "TF/FVIIa complex inhibitors, including TFPI, possess opposing functions by reducing tumor development and metastasis." (PMID 36052162, 2022).
tumor (continued). "Going further, the players of VM, Tissue Factor (TF) and TF pathway inhibitors 1 and 2 (TFPI-1/2) have been found to be crucial for tumour cell-lined tube formation." (PMID 36224457, 2022). "Due to the TFPI decreases, the levels of antiproliferative, antimigratory, and anti-angiogenic mechanisms are abolished, resulting in increased tumour growth, malignancy and metastatic mechanisms." (PMID 29475895, 2018). "TF and its endogenous inhibitor, TFPI are two major players in the coagulation process, acting in an antagonistic manner, as well as in tumour biology where the opposite effect was also discovered." (PMID 29475895, 2018). "They observed a decrease in plasma TFPI levels with tumour size and the grade of malignancy, which is in-line with our findings." (PMID 29475895, 2018). "Specific blockade of TF functions in tumor cells by TF knockdown, monoclonal antibody (mAb) or by tissue factor pathway inhibitor (TFPI) resulted in inhibition of tumor growth, metastasis and angiogenesis." (PMID 28938620, 2017). "Unfortunately, MDA-MB-231 cells exhibit minimal selectin-mediated rolling and we cannot use this cell line to test if selectin-mediated rolling would promote adhesion of tumor cells to immobilized TFPI in our in vitro system." (PMID 25849335, 2015). "Increasing the concentration of FVIIa from 10nM to 100nM significantly increased adhesion to TFPI at 0.35dyn/cm2, showing that FVIIa was indeed limiting the number of TF ligands on the tumor cells that are available to interact with TFPI under shear." (PMID 25849335, 2015). "Using a microfluidic device, we showed for the first time that high TF-expressing tumor cells also bound under low physiological shear to channels coated with immobilized recombinant TFPI." (PMID 25849335, 2015). "We identified several TFPI SNPs (with haplotype effects) that were more frequent in specific clinicopathological tumor characteristics, such as tumor size, triple-negative status and lymph node status, as well as basal and luminal B tumor subtypes." (PMID 25882602, 2015). "After characterizing the tumor cells as a model system for TF-expressing cells, we proceeded to evaluate their adhesion to TFPI under static conditions." (PMID 25849335, 2015). "Using microfluidic devices, we are able to study the interaction between TF-expressing tumor cells and immobilized TFPI to determine if arrest of TF-expressing tumor cells to TFPI was possible under shear." (PMID 25849335, 2015). "Some of the SNPs that followed distinct clinical groups (rs3213739, rs8176479, rs2192824, rs8176541 and rs10153820) also correlated with total TFPI (α + β), TFPIα or TFPIβ tumor mRNA expression, or total TFPI plasma levels." (PMID 25882602, 2015). "Supporting the in vitro observations, in vivo studies have demonstrated that both circulating recombinant TFPI and TFPI-expressing tumor cells significantly attenuated tumor growth and lung metastasis in mice." (PMID 25882602, 2015). "Experimental studies suggest that tissue factor (TF) and tissue factor pathway inhibitor (TFPI) are involved in cancer biology as a tumor- promoter and suppressor, respectively, but the clinical significance is less clear." (PMID 25882602, 2015). "TF and TFPI exert opposing effects in coagulation, but also in cancer biology; although TF seems to be a tumor-promoting factor, TFPI exerts tumor suppressor activities." (PMID 25882602, 2015). "This is the first study showing that TF-expressing tumor cells can be captured by immobilized TFPI, a ligand constitutively expressed on the endothelium, under low shear in vitro." (PMID 25849335, 2015). "In this study, we demonstrated that TF-expressing tumor cells bind to immobilized purified TFPI in vitro under low physiological shear." (PMID 25849335, 2015). "This binding and arrest of TF-expressing tumor cells to TFPI is dependent on the shear stress, coating concentration of TFPI, and FVIIa concentration." (PMID 25849335, 2015).